HPRT1 (hypoxanthine phosphoribosyltransferase 1)
Diseases named in the same sentence as HPRT1 in open-access papers (continued):
Sharing a sentence is not in itself a finding about the gene and the disease.
breast carcinoma (16 papers, 2007 to 2024). "We found that high HPRT1 or NT5E expression was closely associated with inferior overall survival in patients with lung or breast cancers." (PMID 34703880, 2021). "Our results revealed that HPRT1 expression is elevated in a majority of the cancers, including breast cancer, and is a critical regulator of cellular pathways associated with rapid cell growth in basal subtype breast tumors." (PMID 32532008, 2020). "Collectively, these results clearly showed a causal relationship between HPRT1 expression and basal breast cancer." (PMID 32532008, 2020). "Altogether, these results suggest that HPRT1 is associated with breast cancer progression and is a potential prognostic marker." (PMID 32532008, 2020). "Experimental results support the association between HPRT1 and breast cancer metastasis risk." (PMID 38875364, 2024). "Additionally, our study explored the underlying mechanism of the Metastasis Score and its association with tumor immunity, focusing on HPRT1 gene expression in breast cancer tissues of transfer and untransferred groups using experimental methods." (PMID 38875364, 2024). "Our results show that low expression of HPRT1 was associated with improved prognosis of HER2-positive breast cancer, which may be related to HPRT1’s involvement in the purine rescue pathway." (PMID 35663326, 2022). "Based on the results of immunohistochemistry, we found that the HPRT1 staining of breast cancer tissues in 5 cases of the transfer group was significantly deeper, while that in the untransferred group was lighter." (PMID 38875364, 2024). "While TBP (mean Cq ± SD = 29 ± 2.59) and HPRT1 (mean Cq ± SD = 25.36 ± 1.311) were the least abundant reference genes in hepatic and breast cancer cell lines, respectively." (PMID 34752497, 2021). "In breast cancer cells, similar to geNorm and NormFinder that ranked HPRT1 as the first five stable reference genes, BestKeeper also indicated HPRT1 as the only nominee with SD<1 (0.85)." (PMID 34752497, 2021). "Further, in breast cancer, the subtype-specific analysis showed that its expression was highest in basal and triple-negative breast cancer, and HPRT1 knockdown in breast cancer cells suggested that HPRT1 positively regulates genes related to cancer pathways." (PMID 32532008, 2020). "HPRT1 expression levels varied widely in a large cohort of both normal and malignant samples of different tissue origin, with breast cancer exhibiting the highest average HPRT1 compared to other malignancies." (PMID 32532008, 2020). "Our analysis clearly demonstrated that HPRT1 expression was significantly upregulated in breast cancer, most notably in the basal subtype." (PMID 32532008, 2020). "The knockdown of HPRT1 was performed using two different siRNAs in the triple-negative MDAMB231 breast cancer cell line, and we performed differential gene expression analysis of RNA-seq data." (PMID 32532008, 2020). "The top seven HPRT1-downregulated genes shown in the heatmap were evaluated across different molecular subtypes and were found to be preferentially expressed in basal breast cancer molecular subtype tumor samples." (PMID 32532008, 2020). "Since HPRT1 expression was highest in the basal molecular subtype of breast cancer, we chose the MDAMB231 breast cancer cell line as a representative to understand HPRT1’s role in regulating key tumorigenic genes and pathways." (PMID 32532008, 2020). "To identify HPRT1-regulated pathways in basal breast cancer, we evaluated the relative RNA expression of HPRT1 in cell lines representing different molecular subtypes of breast cancer." (PMID 32532008, 2020). "These molecular analyses closely correlated with the effect of HPRT1 expression on clinical outcome, which confirmed the subtype-specific role of HPRT1 in breast cancer." (PMID 32532008, 2020).
breast carcinoma (continued). "The KLK5 expression of the benign tissue specimens ranged between 0.035-1380.4×103 KLK5 mRNA copies/103 HPRT1 mRNA copies (c/Kc), while the expression in the tissue specimens obtained by the breast cancer patients varied between 0.035-19.6x103 c/Kc." (PMID 21906360, 2011). "Importantly, in HER2-positive breast cancer, decreased expression of metabolism-related genes ATIC, HPRT1, ASNS, SULT1A2, and HAL was associated with increased survival." (PMID 35663326, 2022). "Notably, HPRT1 expression was upregulated in breast cancer samples, prompting interest in further examining the role of HPRT1 in this cancer." (PMID 32532008, 2020). "With the knowledge that HPRT protein levels are significantly upregulated in basal subtype breast cancer compared to normal samples, we performed gene expression analysis and identified HPRT1-regulated pathways that are possibly crucial in breast cancer biology." (PMID 32532008, 2020). "Interestingly, we also found HPRT1 expression to be highest in the basal subtype of breast cancer patients, which is the most aggressive cancer and remains a difficult molecular subtype to treat due to its heterogeneity." (PMID 32532008, 2020). "Indeed, HPRT1, an enzyme that uses hypoxanthine metabolite to recycle purines (in order to be more efficient in DNA and RNA synthesis), predicts clinical outcome and controls gene expression in breast cancer." (PMID 37108611, 2023). "Compared with normal control tissues, the expression of HPRT1, ASNS, ATIC, SULT1A2, and HAL was significantly increased in HER2-positive breast cancer samples." (PMID 35663326, 2022). "The efficiency and specificity of these primers except hypoxanthine phosphoribosyltransferase 1 (HPRT1), TATA-box binding protein (TBP), and actin beta (ACTB) were also studied in exosomal RNA of hepatic and breast cancer cell lines by our team recently." (PMID 34752497, 2021). "The relative quantification of the KLK5 mRNA expression was performed with the use of the comparative CT (2-ΔΔCT) method, whereas the HPRT1 was employed as endogenous reference gene and the BT20 breast cancer cell line as the calibrator of the assay." (PMID 21906360, 2011). "In addition to basal cell type, we investigated the effect of HPRT1 knockdown in MCF10A (normal breast) and MCF-7 (ER+ breast cancer) cells using global transcriptomic profiling." (PMID 32532008, 2020). "Interestingly, protein abundance of HPRT1, HNRNPA0, IFIT3, CTNND1 and EIF4A3 predicted poor overall survival in breast cancer patients, however, PPM1A association was non-significant." (PMID 32532008, 2020). "In addition, ATIC, HPRT1, ASNS, SULT1A2, and HAL may represent attractive therapeutic targets for HER2-positive breast cancer, and require further validation studies, especially considering that treatment with specific inhibitors may alter the expression of these metabolic genes." (PMID 35663326, 2022).
Dystonia (12 papers, 2011 to 2025). An abnormally increased muscular tone that causes fixed abnormal postures. "A better insight in the pathogenic mechanisms of LND, in which a mutation in the HPRT1 gene causes a complex neurobehavioral phenotype including dystonia, cognitive defects and self-injurious behavior, is crucial for developing new treatment opportunities for this incapacitating disease." (PMID 35660973, 2022). "The IMPDH2 reaction is flanked by HPRT1 products—also a dystonia-linked protein—upstream from GCH1." (PMID 34305140, 2021). "Cerebellar hypometabolism occurred in HPRT1, PANK2, CP-Kernicterus and CP-Preterm, four groups with severe baseline dystonia based on BFMDRS-M scoring." (PMID 36445406, 2023).
prostate carcinoma (11 papers, 2008 to 2023). A carcinoma that arises from epithelial cells of the prostate gland. "Using a set of three reference genes (YWHAZ, GAPDH, and HPRT1), we analyzed myosin 1C isoform A mRNA expression in a set of cancer and non-cancer cell lines and confirmed the specificity of its expression in prostate cancer cells." (PMID 30498638, 2018). "A particularly striking example in this regard, is the contrast between our results and the reported in prostate cancer tissue, where HPRT1 was the most stable gene, and RPL13A and ACTB were the most unstable." (PMID 18226276, 2008). "Moreover, HPRT1 has a higher statistically significant expression on prostate cancer cells and is significantly upregulated in a large proportion of prostate cancer tissue samples." (PMID 35101049, 2022). "Considering prostate cancer cell types, ACTB/GAPDH and ACTB/HPRT1 are the most suitable reference gene combinations for mRNA analysis, and miR-16/miR-1228-3p and RNU6-2/RNU43 for miRNA analysis in AR+, and AR− and normal cell lines, respectively." (PMID 29386530, 2018). "To verify the role of myosin 1C isoform A mRNA expression as a putative prostate cancer marker we performed RT qPCR normalized by three reference genes (GAPDH, YWHAZ, HPRT1) on PC3, RWPE-1, LNCaP and 22Rv1 cell lines." (PMID 30498638, 2018). "Considering prostate cancer cell types, ACTB /GAPDH and ACTB/HPRT1 are suggested to be the most suitable reference gene combinations for mRNA analysis." (PMID 29386530, 2018). "Moreover, TBP has already been used as an RG in several studies on prostate cancer, and in the lymph nodes of a prostate cancer patient, TBP and HPRT1 showed good expression stabilities." (PMID 37558778, 2023).
head and neck squamous cell carcinoma (10 papers, 2009 to 2024). A squamous cell carcinoma that arises from any of the following anatomic sites: lip and oral cavity, nasal cavity, paranasal sinuses, pharynx, larynx, and salivary glands. "Using The Cancer Genome Atlas (TCGA), HPRT1 was found to be highly expressed in various cancer types, especially in head and neck squamous cell carcinoma (HNSCC)." (PMID 35205603, 2022). "We report that hypoxanthine phosphoribosyltransferase (HPRT1) expression levels are increased in head and neck squamous cell carcinoma (HNSCC) tissues." (PMID 34231338, 2021). "HPRT1 expression was found to be upregulated in head and neck squamous cell carcinoma and might be a promising prognostic indicator and treatment target for HNSCC." (PMID 35586208, 2022). "For example, a 7-mRNA signature (AATF, APP, GNPDA1, HPRT1, LASP1, P4HA1 and ILF3) of head and neck squamous cell carcinoma (HNSCC) shows a moderate predictive ability for 5-year OS (AUC for training set, 0.75; testing set, 0.66)." (PMID 31396442, 2019). "Nevertheless, the relationship between the HPRT1 gene and head and neck squamous cell carcinomas (HNSCCs) has not been investigated so far." (PMID 34231338, 2021).
melanoma (10 papers, 2013 to 2023). A malignant, usually aggressive tumor composed of atypical, neoplastic melanocytes. "These siRNA duplexes targeting the coding regions of the different CT-X and the siRNA specific to HPRT1 were individually introduced into the SK-MEL-37 melanoma cell line and the effect on mRNA level examined by real-time quantitative RT-PCR analysis 24-48 hours post transfection." (PMID 23625514, 2013). "In line with this, we found increased expression of the key enzymes of nucleotide salvaging HGPRT (HPRT1), thymidine kinase (TK1) and APRT in melanoma (primary and metastatic) compared to normal skin and benign nevi." (PMID 24941944, 2014). "ACTB, hypoxanthine phosphoribosyltransferase 1 (HPRT1), TATA-box binding protein (TBP) and transferrin receptor (TFRC) genes were reported to show a minimal average variation in FFPE and frozen tissue samples of melanoma and other diseases." (PMID 34940125, 2021).
neuroblastoma (10 papers, 2010 to 2024). Neuroblastoma (NB) is the most common solid, extracranial childhood tumor. "Previous studies with qPCR have found HPRT1 and SDHA to show low expression variability in primary neuroblastoma and also, specifically for the SY5Y line, GAPDH, M-RIP, and POLR2F were found to be reliable genes to be used as normalization factors." (PMID 34066513, 2021). "For 34 neuroblastoma samples, the proposed new algorithm yielded the smallest upper bound for the variance of the geometric mean of six genes, ACTB, B2M, GAPDH, HPRT1, TBP, and YWHAZ." (PMID 20470420, 2010).
lung carcinoma (9 papers, 2008 to 2025). "Comprehensive analysis of clinical lung cancer datasets further supported the therapeutic potential of carnosine and its association with HPRT1‐mediated carnosine regulation." (PMID 41365579, 2025). "CARNS1 expression was further evaluated in publicly available lung cancer datasets, including both cell line and clinical tumor cohorts, to determine its association with patient prognosis and its correlation with HPRT1 expression." (PMID 41365579, 2025). "Considering results from both softwares, PPIA, RPLPO, GAPDH, HPRT1, and 18S can be considered accurate reference genes in lung cancer cell lines." (PMID 19014639, 2008). "Furthermore, analysis of clinical databases showed that high CARNS1 expression correlated with improved prognosis in patients with lung cancer and negatively correlated with HPRT1 expression in tumor tissues." (PMID 41365579, 2025). "In human lung cancer, tumors with markers of low oxidative mitochondrial metabolism exhibit enhanced expression of the salvage enzyme hypoxanthine phosphoribosyl transferase 1 (HPRT1) and high levels of the HPRT1 product inosine monophosphate." (PMID 38876105, 2024). "GAPDH and HPRT1 have been recommended as suitable reference genes for lung cancer research." (PMID 19014639, 2008). "We also investigated the relationship between HPRT1 and CARNS1 expression using CCLE (lung cancer cell lines cultured in 2D) and TCGA (clinical lung cancer tissues) databases." (PMID 41365579, 2025).
glioblastoma (8 papers, 2009 to 2024). The most malignant astrocytic tumor (WHO grade IV). "Conversely, HPRT1 was upregulated in normal tissues of glioblastoma multiforme (GBM), kidney renal clear cell carcinoma (KIRC), and kidney renal papillary cell carcinoma (KIRP)." (PMID 38159260, 2024). "Here we show that amongst seven frequently used housekeeping genes TBP and HPRT1 are adequate references for glioblastoma gene expression analysis." (PMID 19257903, 2009). "Altogether, our data show the relevance of previous validation of candidate control genes for each experimental model and indicate TBP plus HPRT1 as suitable references for studies on glioblastoma gene expression." (PMID 19257903, 2009). "To assess whether POLE deficiency affects mutation rate in glioblastoma cells, we performed a HPRT1 mutation assay in POLE WT and KO LN-229 glioblastoma cells." (PMID 37990341, 2023). "For glioblastoma, it was demonstrated that TBP plus HPRT1 are suitable reference genes for normalization purposes in gene expression profiling studies." (PMID 19257903, 2009).
glioma (8 papers, 2014 to 2025). A benign or malignant brain and spinal cord tumor that arises from glial cells (astrocytes, oligodendrocytes, ependymal cells). "Using publicly available RNAseq data from patients bearing pediatric high-grade gliomas (pHGG), we found that H3K27M pHGG tumors expressed less HPRT1 transcript, which encodes HGPRT." (PMID 38594734, 2024). "Analysis of the TCGA database revealed that HPRT1 expression was higher in GBMs than in low-grade gliomas." (PMID 37737247, 2023). "The mRNA expression level of the MCM family members were examined in 59 human glioma samples and six normal brain tissues by qPCR (n = 3), normalized to 18S rRNA and HPRT1 levels." (PMID 25046975, 2014). "Actb, FBXW7 and HPRT1 were differentially expressed between glioma samples and non-tumour controls and were therefore excluded as housekeeping genes." (PMID 41034696, 2025). "The PPIA, H2AFZ, and HPRT1 genes have been proven to be the most stable reference genes in mouse oocytes and preimplantation-stage embryos under different culture conditions, while HPRT1 and RPL13A have been demonstrated to be the most stable reference genes in glioma stem cells (GSCs)." (PMID 37170359, 2022).
colorectal cancer (6 papers, 2020 to 2022). A primary or metastatic malignant neoplasm that affects the colon or rectum. "Instead of PPAT, hypoxanthine phosphoribosyltransferase 1 (HPRT1) was significantly associated with poor prognosis in colorectal cancer, suggesting that the salvage pathway of nucleotide biosynthesis is dominant over the de novo pathway in this cancer type." (PMID 32184390, 2020). "Studies from various cancers, such as colorectal cancer, have shown elevated levels of HPRT1 in tumor samples compared to normal tissues." (PMID 32532008, 2020). "Additionally, the same study found HPRT1 localizes to the surface of the cell membrane in more progressive types of colorectal cancer." (PMID 32532008, 2020).
oral squamous cell carcinoma (6 papers, 2022 to 2024). "HPRT1 has also been found to promote cisplatin resistance by activating phosphoinositide 3-kinase (PI3K)/AKT pathway in oral squamous cell carcinoma." (PMID 39343971, 2024). "In both HNSCC and its subclass oral squamous cell carcinoma, multiple studies have demonstrated that HPRT1 was overexpressed and significantly correlated with the poor prognosis of patients." (PMID 35844514, 2022). "Hypoxanthine phosphoribosyl transferase 1 (HPRT1) regulates the production of purines and inosine involved in the cell cycle and can enhance chemoresistance via the MMP1/PI3K/Akt axis in patients with oral squamous cell carcinoma." (PMID 36969232, 2023). "Therefore, we measured HPRT1 expression in human cancer tissues and adjacent non-carcinoma tissues (ANT) and explored the relationship between HPRT1 expression and clinical pathological factors and prognosis in patients with oral squamous cell carcinoma (OSCC), a common type of HNSCC." (PMID 35205603, 2022).
lung adenocarcinoma (5 papers, 2022 to 2024). A carcinoma that arises from the lung and is characterized by the presence of malignant glandular epithelial cells. "Analysis of The Cancer Genome Atlas (TCGA) showed higher expression of HPRT1 in human lung adenocarcinomas and squamous cell carcinomas compared to nonmalignant lungs." (PMID 38876105, 2024).
breast tumor (4 papers, 2007 to 2023). "A comparison of breast tumor and normal breast tissue showed significantly higher HPRT1 expression in breast tumor samples when compared to normal TCGA and GTEx breast." (PMID 32532008, 2020). "The results showed that over time, breast tumors with higher HPRT1 expression had shorter DMFS, corresponding to poorer clinical outcomes." (PMID 32532008, 2020). "Breast tumors with higher HPRT1 expression showed a worse clinical outcome, and its knockdown in the triple-negative basal-type MDAMB231 cells showed significant alteration in the expression of genes involved in Notch and ErbB signaling pathways." (PMID 32532008, 2020). "Among genes downregulated by HPRT1 knockdown in MDAMB231, their expression was higher in ER- than ER+ breast tumors." (PMID 32532008, 2020). "The expression of six HKs (TFRC, GUSB, GAPDH, ACTB, HPRT1 and RPLP0) was investigated using geNorm and NormFinder softwares in forty breast tumor, four normal and eight adjacent tissues." (PMID 21702980, 2011).
colon carcinoma (4 papers, 2007 to 2019). "Two pairs of genes, HPRT1/PPIA and IPO8/PPIA, were identified to be suitable to normalize gene expression data in metastatic and non-metastatic colon cancer patients, according to geNorm and NormFinder respectively." (PMID 21059236, 2010). "We identified two pairs of genes, HPRT1/PPIA and IPO8/PPIA, which may be suitable to normalize gene expression data in studies conducted in metastatic and non-metastatic colon cancer patients." (PMID 21059236, 2010).